RN7SL732P (RNA, 7SL, cytoplasmic 732, pseudogene)
Gene: Miscellaneous RNA gene on chromosome X (39,786,524 to 39,786,823, reverse strand). Ensembl gene ENSG00000264618.
Homologues: Orthologues: chimpanzee Metazoa_SRP (99% identical), macaque Metazoa_SRP (92% identical). Paralogues in human: RN7SL2 (86% identical), RN7SL1 (86% identical), RN7SL3 (85% identical), RN7SL118P (83% identical), RN7SL113P (82% identical), RN7SL357P (82% identical), RN7SL398P (82% identical), RN7SL322P (81% identical), RN7SL559P (81% identical), RN7SL122P (81% identical), RN7SL126P (81% identical), RN7SL408P (81% identical), and 705 more.